PRAM1 (PML-RARA regulated adaptor molecule 1)
Description:
May be involved in myeloid differentiation. May be involved in integrin signaling in neutrophils. Binds to PtdIns(4)P.
Synonyms: PRAM-1; PML-RAR
Tractability: Antibody: its Gene Ontology location is reachable by antibodies, with medium confidence. PROTAC: its protein half-life has been measured.
Gene: Protein-coding gene on chromosome 19 (8,490,056 to 8,502,647, reverse strand). Ensembl gene ENSG00000133246.
Subcellular location (Human Protein Atlas): Golgi apparatus
Gene Ontology:
Molecular function: protein binding; protein kinase binding
Biological process: integrin-mediated signaling pathway; protein localization to plasma membrane; T cell receptor signaling pathway
Cellular component: protein-containing complex; plasma membrane
Genetic constraint (gnomAD): Loss-of-function variants: 42 observed, 52.98 expected, observed/expected ratio (o/e) 0.79, 90% interval 0.62 to 1.02. The upper end of that interval is the gene's LOEUF score, 1.02, which puts it in group 4 of 6, group 1 being the genes least tolerant of losing a copy. Missense variants: 891 observed, 872.45 expected, observed/expected ratio (o/e) 1.02, 90% interval 0.97 to 1.08. Synonymous variants: 399 observed, 373.07 expected, observed/expected ratio (o/e) 1.07, 90% interval 0.99 to 1.16.
Homologues: Orthologues: chimpanzee PRAM1 (95% identical), macaque PRAM1 (86% identical), dog PRAM1 (62% identical), pig PRAM1 (60% identical), rabbit PRAM1 (60% identical), mouse Pram1 (56% identical), guinea pig PRAM1 (55% identical), tropical clawed frog pram1 (17% identical). Paralogues in human: FYB1 (23% identical), FYB2 (16% identical).
Diseases named in the same sentence as PRAM1 in open-access papers:
PRAM1 is named in the same sentence as 9 diseases in open-access papers, as found by Europe PMC text mining. Sharing a sentence is not in itself a finding about the gene and the disease. The quoted sentences say what the papers report.
leukemia (6 papers, 2015 to 2024). A malignant (clonal) hematologic disorder, involving hematopoietic stem cells and characterized by the presence of primitive or atypical myeloid or lymphoid cells in the bone marrow and the blood. "However, it is also reported that PRAM1 enhanced cell growth in leukemia." (PMID 32924329, 2020). "The genes in the leukemia cell line term were AFDN (alias MLLT4, chromosome 1, WHWT), KLF3 (chromosome 3, LR), RPS6, (chromosome 5, LR), and FCER2, MCOLN1, and PRAM1 on chromosome 20 (GSD)." (PMID 36482174, 2022).
acute myeloid leukaemia (2 papers, 2010 to 2011). "It was thought that Pram1 might be a negative regulator of neutrophil differentiation since it is repressed in acute myeloid leukaemia." (PMID 21085469, 2010).
asthma (1 paper, 2019). "With regards the unmet need for asthma biomarkers, we identified various mRNAs in the circulation that were uniquely expressed in the asthmatic subjects, including HIST1H3C, PRAM1, RAB6B and CD93." (PMID 31221987, 2019).
colorectal cancer (1 paper, 2020). A primary or metastatic malignant neoplasm that affects the colon or rectum. "Similarly, colorectal cancer patients with high expression of CRIP2, PRAM1, HSPB2 or CERCAM had poorer OS comparing with low expressed groups (logrank = 0.0073, 0.0053, 0.0036 and 0.0023, respectively)." (PMID 33125346, 2020).
promyelocytic leukemia (1 paper, 2012). "PRAM-1 was originally identified in promyelocytic leukemia cells upon all-trans retinoic acid-induced granulocyte differentiation." (PMID 22672517, 2012).
tumor (3 papers, 2020 to 2023). "Based on TCGA analysis for the downregulated genes from our RNA-Seq data, high gene signature comprising of TREM2, CATSPER1, NPL, and PRAM1 in tumor-infiltrating PMN-MDSC predicted poor OS rates in COAD patients." (PMID 33312958, 2020).
PRAM1 also shares sentences with these, for which no sentence is quoted: cancer (1 paper); lung carcinoma (1); periodontitis (1).